INS (insulin)
Diseases named in the same sentence as INS in open-access papers (continued):
Sharing a sentence is not in itself a finding about the gene and the disease.
cancer (continued). "Systemic inflammation, insulin‐dependent glucose handling and alterations in energy‐ and protein metabolism and pharmacokinetics have been proposed as pathophysiological mechanisms explaining the association between low skeletal muscle mass and poor clinical outcomes in older patients with cancer." (PMID 32478975, 2021). "Previous findings have suggested that, among antihyperglycemic medications, insulin and sulfonylureas may increase the risk of cancer by interacting with insulin and insulin growth factor-1 (IGF-1) receptor signalling, which enhances proliferation and carcinogenesis." (PMID 32033451, 2020). "Exogenous insulin administration might be implicated in the pathogenesis of increased cancer risk." (PMID 32570776, 2020). "Moreover, insulin leads to lipid metabolic reprogramming, a hallmark of cancer." (PMID 31315616, 2019). "Previous studies have shown that, among antihyperglycemic medication, insulin and sulfonylurea may increase the risk of cancer by interacting with insulin and insulin like growth factor 1 (IGF-1) receptor signalling, which enhances proliferation and carcinogenesis." (PMID 31518336, 2019). "Increased levels of hormones (such as oestrogen, insulin, insulin-like growth factor, and leptin), free fatty acid-induced production of reactive oxygen species, an altered intestinal microbiome and chronic inflammation are known to be associated with an increased cancer risk in obese subjects." (PMID 31439906, 2019). "Importantly, dysfunction of these regulatory systems and feedback loops promotes chronic overactivation of intracellular insulin signaling and is associated with cancer incidence, whereas the opposite, that is, impaired insulin signaling (resistance), defines T2D." (PMID 30116154, 2018). "Physical activity may mediate numerous pathways associated with cancer progression and the development of other chronic diseases including energy metabolism, insulin, insulin-like growth factor-1, chronic inflammation, the immune system, and antioxidant pathways." (PMID 29385194, 2018). "This approach allowed us to test the hypothesis that glucose metabolism-related genetic variants are associated with increased risk of cancers and that the relationships depend on impaired glucose metabolism symptoms (high insulin, glucose, and HOMA-IR levels)." (PMID 28446149, 2017). "Indeed, glucide restriction associated with weight loss is known to decrease insulin levels and the progression of several different types of cancer, with only a minor effect on homeostasis, because during starvation glucose utilization is replaced by ketones derived from fat." (PMID 28717385, 2017). "However, the results for the other exposure categories showed no persistent differences even though an association between the increased cancer risk and use of insulin glargine would have been expected for the hypothesised effect." (PMID 28573394, 2017). "In addition to its potential for lowering concomitant insulin dose, metformin has been reported to have a number of benefits that might attenuate risk, including cardiovascular benefits, cancer-related benefits, and improved all-cause mortality." (PMID 27152598, 2016). "There are two main hypotheses by which insulin analogues might increase the risk of cancer." (PMID 26187749, 2015). "A significant number of epidemiological studies have suggested that insulin use and daily doses, particularly of the long-acting insulin analog glargine, may be responsible for the association with and strong increase in the risk of cancer." (PMID 25866823, 2015). "Over the past decade several studies have shown that insulin therapy may increase the cancer risk." (PMID 25114970, 2014). "Moreover, several metabolic and hormonal factors that have been associated with increased cancer risk (i.e., abdominal adiposity, insulin, testosterone, estradiol, leptin, and inflammatory cytokines) were all significantly lower in the DR group than in the nonobese controls." (PMID 24628815, 2014).
cancer (continued). "Insulin and IGFs may promote tumor cell growth, which increases risk of cancers." (PMID 24884617, 2014). "However, relatively high(er) concentrations of an insulin analog may not only improve metabolic control but also increase cancer risk by dose-dependent effects on cellular differentiation, growth, and proliferation." (PMID 24904529, 2014). "Moreover, the risk of cancer disease and mortality is higher in patients treated with insulin." (PMID 24752580, 2014). "Thus indirect benefits of metformin is a decrease in insulin, a growth promoting hormone, suggesting that metformin could affect tumor growth and reduce the risk of cancer." (PMID 24391834, 2013). "Furthermore, their cancer risk may be modified by different treatments and modified insulin analogues with distinct receptor-binding characteristics showed different mitogenic potencies in cell lines and animals." (PMID 23805988, 2013). "A possible association between insulin use with cancer risk has long been speculated." (PMID 24171174, 2013). "Thus, metformin can no longer be considered as a bona fide DR mimetic, at least in terms of anti-cancer activity, because tumors harboring the insulin-unresponsive, DR-resistant, PIK3CA-activating mutation H1047R remain sensitive to the anti-tumoral effects of the drug." (PMID 23986086, 2013). "Sulphonylurea and insulin therapy may be associated with an increase in cancer mortality." (PMID 22509138, 2012). "Furthermore, the risk of developing cancer increased with higher dosages of insulin." (PMID 22554284, 2012). "Furthermore, there could be other, still unknown and unidentified factors which are associated with the prescription of insulin and which increase the risk of cancer." (PMID 23209929, 2012). "In addition, retrospective, observational studies on diabetic treatment suggest that long-acting insulin glargine (A21Gly,B31Arg,B32Arg human insulin) may increase the risk of cancer, whereas biguanide metformin may decrease cancer risk and cancer mortality." (PMID 22526616, 2012). "Thus, cancer cell-lines or cancer tissue may be more susceptible to growth stimulation by insulin or insulin analogues than healthy tissue, and some cancer cell-lines may be more susceptible than others." (PMID 21714872, 2011). "Misclassification of biomarkers among cases, such as HDL, insulin, and glucose, is possible, since blood samples were taken at enrollment; therefore, the measurements in some cases may have been affected by weight loss among cases as a result of cancer." (PMID 21915122, 2011). "Whether there was an increased prevalence of cancer associated with insulin use was questioned in the early twentieth century, and there is a growing body of evidence suggesting that diabetes increases the risk of the incidence and mortality from certain cancers." (PMID 19690547, 2009). "While alteration of fatty acid and cytokine release from adipose tissue may underlie the effect of this mutation on insulin sensitivity and the risk of T2D, it is hard to believe that these factors also account for the effect of Pro12Ala polymorphism on cancer and age-related disease." (PMID 19390629, 2009). "Furthermore, several related cancer-predisposing syndromes result directly from germline mutations in central genes in the pathways that seem to couple GSC proliferation with organismal insulin signaling levels, including PTEN and LKB1." (PMID 17150096, 2006). "GPR50 plays roles in various physiological processes, including cancer progression, Notch signaling, and insulin, leptin, and glucocorticoid signaling." (PMID 41666959, 2026). "Kajsa Sjöholm and colleagues examine the link between bariatric surgery and long-term cancer outcomes, focusing on patient subgroups defined by suggested predictors of treatment benefit, such as sex and baseline insulin levels." (PMID 41490246, 2026).
cancer (continued). "Insulin signaling can also modulate the mevalonate pathway by activating the mTOR pathway, particularly in cancer cells with aberrant insulin sensitivity." (PMID 41550359, 2026). "Two commonly cited mechanisms, insulin resistance and inflammation, are postulated to explain exercise’s influence on the modulation of cancer progression." (PMID 41546786, 2026). "Next, we assessed the overall cancer IRs after bariatric surgery versus controls, across the insulin subgroups." (PMID 41490246, 2026). "This study examines the link between bariatric surgery and long-term cancer outcomes, focusing on patient subgroups defined by previously suggested predictors of treatment benefit, such as sex and baseline insulin levels." (PMID 41490246, 2026). "Among female controls, cancer IRs increased across insulin tertiles, ranging from 11.6 cases per 1,000-person-years (95% CI [9.9, 13.7]) in the lowest third to 17.8 cases per 1,000-person-years (95% CI [15.0, 21.2]) in the highest third." (PMID 41490246, 2026). "IGF-1 and IGF-2 secreted by tumor-associated macrophages and myofibroblasts contribute to chemoresistance in PaC by activating insulin/IGF receptors on cancer cells." (PMID 41583513, 2026). "Cancer cachexia is also driven by metabolic alterations, including increased energy expenditure, elevated plasma glucose, and insulin resistance." (PMID 41526343, 2026). "Specific applications, such as glucose-responsive insulin MNs and transdermal cancer therapies, will require rigorous human testing before clinical adoption." (PMID 40136911, 2025). "It has been proposed that dysfunctional WAT contributes to the pathophysiology of cancer by raising systemic levels of leptin, steroid hormones, insulin, and insulin‐like growth factor‐1 (IGF‐1) while lowering the concentration of adiponectin." (PMID 39496581, 2025). "In the mixed‐fiber gastrocnemius, insulin resistance and dysregulated glycolytic metabolism are a possible consequence of early phase cancer cachexia." (PMID 40985218, 2025). "Noteworthily, centroacinar-targeted pancreas contained high number of Aldh1+ cells and apparent acinar (or ductal) cells expressing insulin, suggesting the existence of multipotent cancer stem cell." (PMID 39548190, 2025). "In several mouse models of cancer, an insulin supressing diet prevented glucose and insulin increases in response to PI3K inhibitors and significantly improved antitumor efficacy." (PMID 40360883, 2025). "In cancer patients, where therapies can impair insulin sensitivity or induce adverse metabolic side effects, maintaining optimal glucose regulation becomes crucial in preventing further cardiovascular and renal complications." (PMID 40227756, 2025). "Developed into tablets, microparticles, nanoparticles, micelles, and hydrogels, these systems support oral vaccination, insulin delivery, cancer targeting, wound healing, and controlled release." (PMID 41470971, 2025). "Adiponectin is a cytokine also produced by adipose cells, which improves insulin sensitivity, reduces inflammation, and its circulating levels are reduced in cancer patients." (PMID 39941833, 2025). "Currently, the Adapted Physical Activity for Children treated for Cancer and Insulin-Sensitivity study is investigating the metabolic and physical effects of low- versus high-intensity exercise programs initiated as early as the time of cancer diagnosis." (PMID 41437177, 2025). "The findings revealed that MPs experience severe shortages in essential medications, with insulin, antiepileptics, and cancer treatments unavailable in over 90% of cases." (PMID 40961024, 2025). "These pathways include the EGFR tyrosine kinase inhibitor resistance signaling pathway, signaling pathways in cancer, insulin resistance signaling pathway, and chemical carcinogen–receptor activation signaling pathway, among others." (PMID 40733369, 2025).
cancer (continued). "promoting cancer cell apoptosis cell-cycle arrest;anti-inflammatory and antioxidant properties, neuroinflammation and apoptosis reduction;enhancing insulin sensitivity." (PMID 40709093, 2025). "The IGF/insulin system, comprising insulin-like growth factors and insulin, has potent mitogenic and pro-migratory functions, significantly contributing to various cancer types, including BC." (PMID 39942467, 2025). "Pharmacological interventions such as metformin, which lowers blood glucose levels and improves insulin sensitivity, have shown promise in reducing cancer incidence and improving treatment outcomes." (PMID 40387523, 2025). "Insulin, as the primary anabolic metabolic hormone, stimulates cell proliferation, and it is thought to directly stimulate cancer cell proliferation and metastasis." (PMID 41164182, 2025). "By interfering with insulin action, resistin contributes to the development of insulin resistance, a key factor in metabolic disorders such as type 2 diabetes, and cancers such as breast, colorectal, pancreatic and endometrial." (PMID 40551741, 2025). "These included chemical carcinogenesis—receptor activation, insulin resistance, metabolic pathways, pathways in cancer, serotonergic synapse, arachidonic acid metabolism, and efferocytosis." (PMID 40565639, 2025). "Existing epidemiological evidence suggests that excess body weight influences cancer development through several mechanisms, including chronic inflammation, insulin resistance, altered levels of sex hormones, and dysregulated adipokine signaling." (PMID 40469681, 2025). "Evidence from human and animal studies indicates that exercise-induced weight loss reduces circulating levels of IGF-1, insulin, and leptin, thereby downregulating IGF-1-related pathways and promoting cell cycle arrest and cancer suppression." (PMID 40731797, 2025). "The two studies investigating Western dietary patterns or diets classified as being high inflammatory, hyperinsulinaemic, and insulin-resistant showed increased mortality rate, decreased quality of life, and increased cancer recurrence." (PMID 40941553, 2025). "In insulin-resistant states, where circulating free fatty acids are elevated, cancer cells can increase their reliance on fatty acid oxidation." (PMID 41002547, 2025). "Dietary interventions, on the other hand, offer promising strategies to modulate insulin and IGF-1 signaling and reduce cancer risk." (PMID 40428567, 2025). "Our sample population contained few insulin-treated patients, and insulin has been reported to have a cancer-promoting effect." (PMID 40136342, 2025). "Insulin thus drives the cancer cell phenotype via transcriptional reprogramming and downregulation of mitochondrial apoptosis capability." (PMID 41586225, 2025). "Metformin, a cornerstone in T2DM management, has shown promise in reducing PC risk and improving outcomes by lowering insulin and IGF-1 levels and activating AMP-activated protein kinase pathways, thereby inhibiting cancer cell growth." (PMID 40732935, 2025). "Pathways related to extracellular matrix (ECM) remodeling, cell adhesion, and insulin signaling were among the most prominently enriched, indicating platelets’ contribution to cancer beyond their signaling." (PMID 41226816, 2025). "Small-scale studies of faecal microbiota transplantation (FMT) have also suggested that engraftment of donor microbiota can improve insulin sensitivity or enhance responses to cancer therapy in selected settings [PMID: 37929014]." (PMID 41374093, 2025). "Insulin is a crucial regulator of nutrient metabolism in adipocytes, muscle, and liver, but also has mitogenic effects in cancer cells." (PMID 41178720, 2025). "miR-CRAFT is a well-controlled study, and the study population is balanced for two major confounders of miR expression, cancer and insulin treatment." (PMID 40257717, 2025).
cancer (continued). "Through altered levels of cytokines, insulin, and extracellular vesicles—among other factors—the obese state promotes cancer cell de‐differentiation and facilitates the release of cancer cells from the primary tumor." (PMID 39496581, 2025). "Although insulin’s impact has been addressed in different cancer models, the impact of glucagon and hyperglucagonemia (>100 pmol/mL) on the TME and consequent effect on cancer metabolic remodelling is not well understood." (PMID 40649254, 2025). "In contrast, high adipose tissue levels provide a survival advantage for patients with cancer, as subcutaneous adipose is metabolically stable and produces leptin, improving insulin sensitivity." (PMID 40385349, 2025). "Both insulin-expressing cancer cell populations expressed beta cell, insulin, and glucose-related genes, including known neuroendocrine genes such as chromogranins, secretogranins, and IAPP (islet amyloid polypeptide)." (PMID 40438247, 2025). "Evexomostat is a novel antiangiogenic and antimetastatic drug candidate which also has insulin-sensitizing and antiobesity properties that is being developed for use in combination with standard-of-care therapies for obese patients with cancer." (PMID 40444533, 2025). "SO can establish a metabolic and inflammatory environment that facilitates the development and progression of cancer, involving mitochondrial dysfunction, oxidative stress, insulin resistance, hormonal dysregulation, and chronic inflammation." (PMID 41007166, 2025). "Additional growth factor such as B27, FGF and insulin are required for spheroid formation for most cancer cells." (PMID 39792296, 2025). "Metabolic alterations, including lipid and glucose metabolism, insulin resistance, and inflammation, are known to interact in complex ways and contribute to cancer progression." (PMID 40313248, 2025). "These nanomaterials show promise in oral vaccines, insulin delivery, cancer targeting, wound dressings, and heavy metal removal, with some also used in green synthesis of antimicrobial, antioxidative, and anticancer metal nanoparticles." (PMID 41470971, 2025). "Both male and female 6mGHRKO mice exhibited reduced oxidative stress, with males showing improved insulin sensitivity and resistance to cancer, while females demonstrated extended lifespan." (PMID 41350448, 2025). "Research on insulin analogues and anti-insulin receptor antibodies highlights the role of insulin signaling in cancer progression." (PMID 41195424, 2025). "Metformin primarily reduces hepatic glucose production and lowers circulating insulin levels, thereby decreasing insulin/IGF‐1 receptor activation in cancer cells." (PMID 40387523, 2025). "High insulin levels can also promote tumor cell growth by stimulating DNA synthesis and inhibiting apoptosis, thereby facilitating cancer cell invasion and metastasis." (PMID 41296433, 2025). "When these cancer subtypes were combined, GLP-1R agonist use for T2D management reduced the risk for all hematologic malignancies by 54% compared with insulin." (PMID 41178720, 2025). "An increase in insulin or IGF-1 levels, commonly seen in T2DM, is strongly associated with increased cancer risk and mortality." (PMID 40764810, 2025). "Its antitumor effects are mediated by AMPK activation, mTOR inhibition, suppression of insulin-mediated gluconeogenesis, and improved insulin sensitivity, which reduce cancer-promoting metabolic conditions." (PMID 40450131, 2025). "This activation, instigated by obesity, augments the metabolic reprogramming within cancer cells, propelled by the triad of adipogenesis, insulin perturbations, and hypoxic microenvironments." (PMID 39969135, 2025). "This profile supports further evaluation of these energy restricted dietary approaches for cancer prevention particularly in those with high levels of ectopic fat and insulin resistance." (PMID 41146360, 2025).